CNTN1 (contactin 1)
Diseases named in the same sentence as CNTN1 in open-access papers (continued):
Sharing a sentence is not in itself a finding about the gene and the disease.
Ataxia (10 papers, 2021 to 2025). Ataxia refers to impaired coordination of voluntary muscle movement. "Conversely, deficiency in CNTN1 (Contactin 1) leads to animals developing normally until approximately P10, after which they fail to thrive, exhibiting symptoms such as ataxia and anorexia, and typically succumb between P16 and P18." (PMID 39570887, 2024). "Given that ataxia is a prevalent sign of Miller–Fisher syndrome, associated with GT1a and GQ1b antibodies, it raises the question of whether the ataxia in this case is caused by the CNTN1 antibody or antiganglioside antibodies (GT1a and GQ1b antibodies)." (PMID 38846936, 2024). "Herein, we report a case of recurrent CNTN1 antibody-positive nodopathy and discuss the possible mechanisms behind tremor and ataxia and the CSF characteristics." (PMID 38846936, 2024). "Here, we report a case of recurrent CNTN1 antibody-positive nodopathy and discuss the possible mechanisms of tremor and ataxia, and the CSF characteristics, to deepen our understanding of the disease." (PMID 38846936, 2024). "Contactin-1 (CNTN1) antibody-positive nodopathy is rare and exhibits distinct clinical symptoms such as tremors and ataxia." (PMID 38846936, 2024). "Ataxia has been identified as a common symptom of CNTN1 antibody-positive nodopathy." (PMID 38846936, 2024). "Cntn1 null mice exhibited severe ataxia, progressive muscle weakness and growth retardation." (PMID 36614124, 2022). "Interestingly, the null mouse model of Cntn1, encoding the IgSF-CAM contactin, which is a functional binding partner of VGSC β1 subunits, has a similar phenotype to Scn1b null mice, including death by P18, severe ataxia, and cerebellar micro-organization defects with aberrant CGN axon guidance." (PMID 40923316, 2025). "At present, the mechanism of tremor and ataxia in CNTN1 antibody-positive nodopathy is still not clear, and further research is needed." (PMID 38846936, 2024). "Patients with anti-CNTN1 antibodies present with an acute or subacute onset course with a prevalent distal weakness, ataxia, and no or poor response to IVIg." (PMID 39050350, 2024). "Although contactin-1 can bind directly to the cerebellar structure, the result of anti-CNTN1 antibody testing in CSF was negative, supporting the view that ataxia is caused by proprioceptive impairment rather than cerebellar lesions." (PMID 34675937, 2021).
lung adenocarcinoma (10 papers, 2010 to 2025). A carcinoma that arises from the lung and is characterized by the presence of malignant glandular epithelial cells. "Our previous study revealed that CNTN-1 upregulation in lung adenocarcinoma patients was correlated with lymphatic invasion during platinum-based chemotherapy." (PMID 35711928, 2022). "This suggests the role of CNTN1 as a potential biomarker to predict and evaluate the chemotherapeutic efficacy, especially in patients with lung adenocarcinoma." (PMID 33194679, 2020). "CNTN1 expression at the mRNA and the protein levels was significantly higher in cisplatin-resistant lung adenocarcinoma cells than in the control." (PMID 33194679, 2020). "In in vivo studies, CNTN1 knockdown in a xenograft mouse model of cisplatin-resistant lung adenocarcinoma also reversed cisplatin resistance and reduced the metastasis potency." (PMID 33194679, 2020). "Recently, several studies have revealed that contactin-1 is an important mediator of the progression of several cancers, including lung adenocarcinoma, squamous carcinoma, and hepatocellular carcinoma." (PMID 32704452, 2020). "Further, in the drug-resistant cell lines derived from small cell lung cancer (SCLC) and lung adenocarcinoma, the CNTN1 and p-AKT levels were increased upon N-cadherin and vimentin upregulation and E-cadherin downregulation." (PMID 33194679, 2020). "In lung adenocarcinoma, CNTN1 plays a key role in mediating metastasis and invasion through the stimulation of Ras homolog gene family, member A (RhoA)." (PMID 29673312, 2018). "Suppression of CNTN-1 expression abolished the ability of lung adenocarcinoma cells to invade Matrigel in vitro as well as the polymerization of filamentous-actin and the formation of focal adhesion structures." (PMID 23606831, 2013). "CNTN-1 was reported expressing in cancers, such as human astrocytic gliomas and lung adenocarcinoma." (PMID 23606831, 2013). "In animal studies, knockdowncontactin-1 resulted in inhibition of tumor metastasis and an increase in survival.In patients with lung adenocarcinoma, high Contactin-1 expressionwas directly correlated with tumor stage, lymph node metastasis and poor survival." (PMID 21079744, 2010). "In vitro experiments on lung adenocarcinoma cells could show that a downregulation of Contactin 1 led to an increased treatment sensitivity against cisplatin, resulting in increased apoptosis." (PMID 41299419, 2025). "Additionally, in our prior studies, CNTN-1 upregulation was revealed to increase metastasis, invasion, and chemoresistance in lung adenocarcinoma cells with cisplatin resistance." (PMID 35711928, 2022). "Knockdown of CNTN1 suppressed invasion and metastasis of lung adenocarcinoma." (PMID 29673312, 2018). "Notably, in vitro silencing of CNTN1 expression may inhibit the invasive and metastatic ability of lung adenocarcinoma cells." (PMID 22580838, 2012). "Among the genes that mapped to the top 100 loci of European-Americans, CNTN1 (Contactin 1, [MIM 600016]) was proposed to have an important function in the invasion and metastasis of lung adenocarcinoma cells." (PMID 23829686, 2013). "There are only few reports that elucidate the relation between CNTN-1 and VEGF-C expression in the growth of primary tumor and lymphatic metastasis in lung adenocarcinoma." (PMID 23606831, 2013).
sensory ataxia (10 papers, 2018 to 2025). Any ataxia in which the causes of the disease is a perturbation of the sensory system, leading to its dysfunction. "Severe proprioceptive loss and sensory ataxia were significantly more frequent in IgG4-seropositive patients and were observed in all patients with anti-CNTN1 antibodies, 2 patients with anti-Caspr1 IgG4 antibodies, and 3 patients with anti-Nfasc155 IgG4 antibodies." (PMID 31753915, 2020). "Three patients with CNTN1-IgG4 were elderly men, who presented with subacute disease progression, sensory ataxia, very high cerebrospinal fluid (CSF) protein levels, and apparent conduction delay in nerve conduction studies." (PMID 40995362, 2025). "Patients who carried anti‐CNTN1 IgG4 antibodies more frequently exhibited sensory ataxia (p = 0.009)." (PMID 38980226, 2024). "Our patients with anti‐CNTN1 nodopathy had significantly more frequent sensory ataxia and a greater incidence of poor response to IVIg, which was consistent with earlier reports." (PMID 38980226, 2024). "In the field of neurological symptoms, sensory ataxia markedly improved, and the titer of anti-CNTN1 antibody as well as CD19+ B cells decreased only two days following low-dose rituximab treatment." (PMID 35958552, 2022). "CNTN1-IgG4 is characterized by elderly onset, acute or subacute disease progression, distal-dominant limb weakness, sensory ataxia, very high CSF protein levels, apparent conduction delay on NCSs, and a poor response to IVIg, consistent with the neurological findings of all cases in this study." (PMID 40995362, 2025). "Additionally, the dorsal root ganglia’s blood–nerve barrier is more permeable, allowing CNTN1 antibodies to infiltrate sensory neurons and axons, which may explain sensory ataxia." (PMID 38846936, 2024).
breast carcinoma (9 papers, 2013 to 2025). "Additionally, expression of CNTN1 was associated with cell proliferation in esophageal, thyroid, and breast cancers." (PMID 33194679, 2020). "However, further investigations will be required to further clarify the mechanisms underlying the effect of CNTN1, and to determine whether CNTN1 expression has any clinical significance in breast cancer, or may represent a potential therapeutic target." (PMID 29673312, 2018). "Some cases with anti-CNTN1 AN had concomitant malignancies including breast cancer, plasmacytoma, lymphoma, and colon adenocarcinoma." (PMID 40995362, 2025). "The relative gene expression of the CNTN-1 gene among the breast cancer cases was higher (4.92-fold) compared to healthy control." (PMID 34659414, 2021). "Overexpression of CNTN-1 promoted tumor growth by enhancing breast cancer cell proliferation, migration, invasion, and cell cycle progression." (PMID 34659414, 2021). "Spearman correlation analysis was done between NRXN-1 and CNTN-1 mRNA expression among breast cancer patients." (PMID 34659414, 2021). "Advanced stage breast cancer cases had 6.89-fold CNTN-1 mRNA expression while being lower in the early-stage breast cancer cases (1.72-fold) and differences among them were found to be statistically significant (p < 0.0001)." (PMID 34659414, 2021). "The present study observed decreased relative miRNA-495 expression (0.07-fold) while an increase in NRXN-1 (11.61-fold) and CNTN-1 (4.92-fold) was observed among breast cancer patients compared to healthy controls." (PMID 34659414, 2021). "The enrichment of the CREIGHTON_ENDOCRINE_THERAPY_RESISTANCE_3 gene set with a role in resistance of breast cancer to endocrine therapy indicates differential expression of CNTN1 and the LE genes in CRPCs." (PMID 33578925, 2021). "The volume and weight of xenograft tumors from nude mice, transfected with breast cancer cells overexpressing CNTN1, were significantly higher than those from the control." (PMID 33194679, 2020). "CNTN1 expression in breast cancer correlates with the expression of genes functioning in cancer-stroma interactions and skeletal system development." (PMID 32752094, 2020). "In a study investigating breast cancer (BC), ectopic CNTN1 overexpression enhanced cell proliferation, invasion, migration as well as cell cycle progression from G1 to S phase in breast cancer cells in vitro." (PMID 32752094, 2020). "In this study, we described the effect of CNTN1 in Hs578T cells; however, we are currently investigating the tumorigenic role of CNTN1 in other breast cancer cells as well as the mechanism by which CNTN1 exerts its effect in breast cancer." (PMID 29673312, 2018). "In this study, we assessed expression of CNTN1 in breast cancer cell lines including MCF7-ADR, MDA-MB-468 MCF7 and Hs578T." (PMID 29673312, 2018). "In this study, we evaluated the expression of CNTN1 in a panel of breast cancer cell lines and investigated the capacity of CNTN1 to regulate cell proliferation, migration and invasion in Hs578T breast cancer cells." (PMID 29673312, 2018). "The effect of CNTN1 overexpression on proliferation, migration and invasion of Hs578T breast cancer cells was assessed in vitro and in vivo." (PMID 29673312, 2018). "The purpose of this study is to investigate the role of CNTN1 in regulating tumor growth, migration and invasion in breast cancer." (PMID 29673312, 2018). "In conclusion, our current study represents proof of concept for the key role of CNTN1 in regulating proliferation, invasion and metastasis in breast cancer." (PMID 29673312, 2018). "Our results indicate that CNTN1 was expressed in these breast cancer cell lines, however CNTN1 expression was lower in Hs578T cell than the other cell lines." (PMID 29673312, 2018). "We first measured the expression of CNTN1 in several breast cancer cell lines (MCF7-ADR, MDA-MB-468, MCF7 and Hs578T) using RT-PCR and western blotting." (PMID 29673312, 2018).
breast carcinoma (continued). "To investigate the role of CNTN1 in breast cancer cells, we induced overexpression of CNTN1 in Hs578T cells by transient transfection with a CNTN1 plasmid." (PMID 29673312, 2018). "To further support our findings, we overexpressed CNTN-1 in two CNTN-1 null breast cancer cell lines expressing E-cadherin." (PMID 23724143, 2013). "CNTN1 overexpression in LNCaP cells resulted in enrichment of the CREIGHTON_ENDOCRINE_THERAPY_RESISTANCE_3 gene set that facilitates endocrine resistance in breast cancer." (PMID 33578925, 2021). "Therefore, the present study aimed to evaluate the prognostic importance of miRNA-495, NRXN-1, and CNTN-1 mRNA expression as well as the association of miRNA-495 expression with NRXN-1 and CNTN-1 mRNA expression among breast cancer patients." (PMID 34659414, 2021). "Evidence supports that CNTN1 promotes cancer-stromal interaction, resulting in activation of a complex network required for cancer progression and metastasis (bone metastasis for breast cancer)." (PMID 32752094, 2020). "Notably, CNTN1 overexpression also enhanced breast cancer xenograft tumor growth in vivo in nude mice." (PMID 32752094, 2020). "However, further investigation is required to understand the mechanism by which CNTN1 influences proliferation, metastasis and invasion in breast cancer." (PMID 29673312, 2018). "Furthermore, CNTN1 promoted migration and invasion of Hs578T breast cancer cells in transwell assays." (PMID 29673312, 2018). "CNTN1 promotes growth, metastasis and invasion of Hs578T breast cancer cell line." (PMID 29673312, 2018). "Thus, Hs578T cells were selected for further experiments to examine the function of CNTN1 in breast cancer cells." (PMID 29673312, 2018). "In addition, since two breast cancer cell lines examined expressed E-cadherin, we proceeded to examine if CNTN-1 can regulated E-cadherin and AKT activity in these two cell lines." (PMID 23724143, 2013). "Correlation analysis showed a significant negative correlation between miRNA-495 expression and NRXN-1 mRNA expression among the breast cancer patients while a positive correlation between NRXN-1 and CNTN-1 mRNA expression was observed." (PMID 34659414, 2021). "However, the role of CNTN1 in breast cancer remains unclear." (PMID 29673312, 2018). "Thus, therapies targeting CNTN1 may prove efficacious for breast cancer." (PMID 29673312, 2018). "HER2 positive breast cancer cases showed slightly higher expression of CNTN-1 mRNA expression (5.92-fold) while HER2 negative breast cancer cases had lower CNTN-1 mRNA expression (4.26-fold) comparatively (p=0.04)." (PMID 34659414, 2021). "Breast cancer cases with positive PR status had 6.19-fold CNTN-1 mRNA expression while PR negative breast cancer cases had 4.44-fold CNTN-1 mRNA expression (p=0.03)." (PMID 34659414, 2021). "Contactin1 (CNTN1) has been shown to play an important role in the invasion and metastasis of several tumors; however, the role of CNTN1 in breast cancer has not been fully studied." (PMID 29673312, 2018). "Breast cancer cases who had lymph node involvement had higher CNTN-1 mRNA expression (5.97-fold) compared to breast cancer cases who did not have lymph node involvement (4.10-fold) and the expression differences between them were found to be statistically significant (p=0.01)." (PMID 34659414, 2021). "In addition, although AKT activation increased after the overexpression of CNTN-1 in MCF7, there was no change in another breast cancer cell line, BT549 despite a change in E-cadherin levels." (PMID 23724143, 2013).
congenital myopathy (9 papers, 2011 to 2022). "A previous report described a CNTN1 mutation that caused a lethal form of congenital myopathy in 4 members of a large consanguineous Egyptian family patients, possibly due to a loss of contactin-1 in the neuromuscular junction." (PMID 30515076, 2018). "Down-regulation of Cntn1 can cause lethal neurodegenerative phenotypes and congenital myopathy in mice." (PMID 27331400, 2016). "A relationship between CMS and dystroglycanopathies has previously been proposed; however, this was for a lethal form of congenital myopathy due to mutations in CNTN1 where affected individuals died at birth or shortly afterwards." (PMID 26133662, 2015). "For example, a mutation in CNTN1, a neural adhesion protein, leads to a familial form of lethal congenital myopathy." (PMID 24968028, 2014). "Since the human disease associated with CNTN1 mutations is categorized as a congenital myopathy, we examined this functionally in muscle." (PMID 22242131, 2011). "In humans, mutations in CNTN1 cause a familial form of lethal congenital myopathy (Compton-North congenital myopathy, OMIM ID# 612540), a disease characterized by congenital onset muscle weakness and myopathic features in biopsy samples." (PMID 22242131, 2011). "In contrast to this GLDN‐associated lethal congenital arthrogryposis and congenital myopathy Compton‐North, resulting from homozygous CNTN1 variants, are only associated with a severe phenotype, leading to death early in life, mostly after the first days, almost independent of the type of variant." (PMID 32779773, 2020). "A study on a consanguineous family with a homozygous contactin-1 mutation presenting with lethal congenital myopathy also supports the role contactin-1 may have in peripheral neuromyopathies." (PMID 29249937, 2017). "In addition, mutations in the CNTN1 gene causing a familial type of lethal congenital myopathy have been reported." (PMID 22580838, 2012). "Taken together, the histopathology, anatomy, and functional analysis of muscles in Cntn1 mutant mice are inconsistent with a congenital myopathy, and suggest that the severe locomotor phenotype is the result of dysfunction in the nervous system, as previously suggested, and not in the muscle itself." (PMID 22242131, 2011). "Although we do not favor this hypothesis, it is a possibility that the CNTN1 mutation identified in patients is not the cause of the lethal congenital myopathy." (PMID 22242131, 2011).